CCR8 (C-C motif chemokine receptor 8)
Description:
G protein-coupled receptor that can bind a variety of chemokines, such as CCL1, CCL8, CCL16, CCL18. Regulates monocyte and eosinophil chemotaxis. Undergoes internalization upon CCL18 binding, leading to induced migration and calcium flux of highly polarized Th2 cells. In microglial cells, promotes phagocytosis with CCL18 through NF-kappa-B and Src signaling pathways. Stimulation of the CCL1-CCR8 signaling axis protects the gut from acute intestinal damage (By similarity). (Microbial infection) Acts as a coreceptor for HIV-1 and HIV-2 viruses. (Microbial infection) Acts as a receptor for Kaposi virus protein vCCL1/K6 and thereby inhibits apoptosis in the targeted cells.
Synonyms: CC-CKR-8; CCR-8; CKR-L1; GPRCY6; CDw198; CKRL1; CMKBR8; CMKBRL2; CY6; TER1; GPR-CY6
Tractability: Small molecule: a structure with a bound ligand is known; a high-quality ligand is known; it belongs to a druggable protein family. Antibody: its Gene Ontology location is reachable by antibodies, with high confidence; UniProt places it where antibodies can reach, with medium confidence; UniProt predicts a signal peptide or a membrane-spanning region. PROTAC: a small molecule that binds it is known.
Target class: Chemokine receptor; Peptide receptor (family A GPCR); Family A G protein-coupled receptor; CC chemokine receptor; Membrane receptor
Chemical probes: CCR8 antagonist 1, CHEMBL380492
Gene: Protein-coding gene on chromosome 3 (39,329,709 to 39,336,269, forward strand). Ensembl gene ENSG00000179934.
Subcellular location: Cell membrane
Pathways (Reactome):
Signal Transduction: Chemokine receptors bind chemokines; G alpha (i) signalling events
Gene Ontology:
Molecular function: G protein-coupled receptor activity; protein binding; C-C chemokine binding; C-C chemokine receptor activity; chemokine receptor activity; coreceptor activity
Biological process: G protein-coupled receptor signaling pathway; calcium-mediated signaling; cell adhesion; cell chemotaxis; chemotaxis; immune response; positive regulation of cytosolic calcium ion concentration; cellular response to cytokine stimulus; chemokine-mediated signaling pathway
Cellular component: plasma membrane; external side of plasma membrane; membrane
Genetic constraint (gnomAD): Loss-of-function variants: 3 observed, 1.4 expected, observed/expected ratio (o/e) 2.14. That is too few expected variants to judge how well the gene tolerates losing a copy. Missense variants: 356 observed, 438.66 expected, observed/expected ratio (o/e) 0.81, 90% interval 0.74 to 0.89. Synonymous variants: 156 observed, 174.25 expected, observed/expected ratio (o/e) 0.9, 90% interval 0.79 to 1.02.
Homologues: Orthologues: macaque CCR8 (94% identical), pig CCR8 (82% identical), rabbit CCR8 (77% identical), guinea pig CCR8 (74% identical), rat Ccr8 (71% identical), mouse Ccr8 (70% identical), tropical clawed frog ccr8 (39% identical), zebrafish ccr8.1 (37% identical), zebrafish cabz01093075.1 (37% identical), zebrafish si:cabz01093077.1 (35% identical), zebrafish si:ch211-207g17.3 (33% identical), zebrafish ccr2 (30% identical), and 1 more. Paralogues in human: CCR4 (43% identical), CCR5 (40% identical), CCR1 (39% identical), CCR2 (39% identical), CX3CR1 (37% identical), CCR3 (36% identical), ACKR2 (33% identical), CXCR2 (31% identical), XCR1 (30% identical), CCR6 (29% identical), CCR9 (29% identical), CXCR1 (29% identical), and 11 more.
Diseases named in the same sentence as CCR8 in open-access papers:
CCR8 is named in the same sentence as 114 diseases in open-access papers, as found by Europe PMC text mining. Sharing a sentence is not in itself a finding about the gene and the disease. The quoted sentences say what the papers report.
breast cancer (30 papers, 2017 to 2025). A primary or metastatic malignant neoplasm involving the breast. "High levels of chemokine receptor C-C motif chemokine receptor 8 (CCR8; encoded by CCR8) are linked to poor prognosis in breast cancer." (PMID 41550427, 2025). "Recently, two reports described the selective expression of the chemokine receptor CCR8 on tumor-associated Treg cells recovered from patients with breast cancer (BC), non-small cell lung cancer (NSCLC), colorectal cancer (CRC) and melanoma (ME)." (PMID 35158783, 2022). "The expression of CCL1 is consistently increased in breast cancer, and there exists a positive association between CCL1 levels and the infiltration of CCR8+ regulatory T cells." (PMID 38730579, 2024). "CCL18 plays a role in promoting breast cancer, colon cancer, and squamous cell carcinoma metastasis, and CCR8 + Tregs are highly suppressive cells within the tumor." (PMID 38281962, 2024). "Previous studies reported shorter overall survival in cancer patients with high CCR8 expression by RNA-seq analysis of breast cancer and lung cancer, and by immunohistochemical and flow cytometric analysis of bladder cancer." (PMID 35354899, 2022). "Activated CCR8+ Tregs have the potential for immunosuppression and are significantly related to the clinical outcome of patients with breast cancer." (PMID 35474948, 2022). "CCL16 binds to chemokine receptors (CCR1, CCR5, and CCR8) to activate angiogenesis in vascular endothelium and is related with prognosis in breast cancer and lung cancer." (PMID 36245978, 2022). "On the other hand, CCR8 was the main chemokine receptor expressed in Tregs from breast cancer, and in Tregs of lung adenocarcinoma, melanoma and colorectal adenocarcinoma in comparison with their counterpart effector population." (PMID 34025655, 2021). "More recently, two analyses of RNAseq of TI Treg cells reported the use of the ratios CCR8/FOXP3 for breast cancer and CCR8/CD3G for lung and colorectal cancers, which had a modest predictive value in terms of overall survival." (PMID 34599187, 2021). "Accordingly, the chemokine receptor CCR8 was identified as part of this signature, supporting previously discussed findings in human breast cancer." (PMID 34632244, 2021). "CCR8 expression was found to be upregulated in Treg cells and correlated with poor survival of patients with breast cancer." (PMID 32047513, 2019). "Treg cells express a high amount of CCR8 and promote breast cancer progression." (PMID 41550427, 2025). "Targeting CCR8 for the depletion of tumor-resident Treg cells might represent a promising immunotherapeutic approach for the treatment of breast cancer." (PMID 39664195, 2024). "A recent study on breast cancer showed that CCR8+ Tregs, a subset of peripheral blood Fr." (PMID 35474948, 2022). "Additionally, intratumoral Tregs from breast cancer tumors have increased expression of the chemokine receptor CCR8, suggesting a unique phenotype and function of these cells in human breast cancer patients." (PMID 36387071, 2022). "As a result, targeting CCR8+ Treg cells through anti-CCR8 mAb or anti-CCL1 neutralizing mAb provides an opportunity for the selective depletion of Treg cells as an immunotherapeutic approach for the treatment of breast cancer." (PMID 34868991, 2021). "Targeting CCR8 to inhibit the migration of tumour-resident Tregs might represent a promising immunotherapeutic approach for the treatment of breast cancer." (PMID 32680511, 2020). "Notably, in breast cancer, CCR8 were upregulated in tumour-resident Tregs compared to their levels in normal tissue-resident Tregs." (PMID 32680511, 2020). "Therefore, we examined the expression of PITPNM3 and CCR8 in T cell subsets from PB of breast cancer patients." (PMID 28290464, 2017). "PITPNM3 and CCR8 are reported CCL18 receptors on breast cancer cells and Th2 cells, respectively." (PMID 28290464, 2017).
breast cancer (continued). "Finally, analysis of the breast samples from the The Cancer Genome Atlas data sets revealed a strong association of CCR8 mRNA amounts normalized to FOXP3, but not FOXP3 mRNA amounts alone, with poor prognosis, suggesting a detrimental role for CCR8‐expressing Treg cells in breast cancer progression." (PMID 31032905, 2019). "In breast cancer, tumour‐derived chemokines such as CCL22 and CCL1 bind to CCR4 and CCR8 on Tregs, guiding their migration into tumour tissues." (PMID 41200753, 2025). "Specifically, in breast cancer, the chemokine receptors that exhibited the most significant correlations were CCR2, CCR4, CCR5, CCR6, CCR8, CXCR2, and CX3CR1." (PMID 40649753, 2025). "The study conducted by Kuehnemuth and co-authors (2018) found a strong correlation between a high presence of CCR8+FOXP3+ Tregs and a worse prognosis in breast cancer patients." (PMID 38730579, 2024). "The results showed that the expression of SLC31A1 was significantly positively correlated with immune markers in breast cancer, especially for STAT3 of Th17 (r = 0.382, p < 0.001), STAT1 of Th1 (r = 0.358, p < 0.001), and CCR8 of Treg (r = 0.304, p < 0.001)." (PMID 37275369, 2023). "Of them, CXCL10, CXCL9, CCL11, CCR8, and GNG13 up-regulate breast cancer, while the other genes download-regulate breast cancer." (PMID 31874629, 2019). "Moreover, phenotyping of human breast cancer infiltrating Treg revealed high expression of CCR8 as compared to peripheral blood Treg and CCR8 expression on intratumoral Treg had a negative impact on clinical outcome." (PMID 30572845, 2018). "Consistently, in the scRNA-seq analysis of the breast cancer microenvironment, CCR6 and CCR8 were predominantly expressed in lymphocytes, not fibroblasts." (PMID 36418470, 2023).
melanoma (17 papers, 2015 to 2025). A malignant, usually aggressive tumor composed of atypical, neoplastic melanocytes. "Increased CCR8 expression has been observed in tumor cells of malignant melanoma and is involved in metastasis to peripheral lymphoid organs." (PMID 40433389, 2025). "Similar observations were made in patients with melanoma, corroborating the notion that CCR8 expression can be used as a marker of ti-Tregs in distinct human cancer types." (PMID 33589525, 2021). "Recently, the chemokine CCL1 and its receptor CCR8 were demonstrated to be important for melanoma cell entry into TDLNs." (PMID 29527513, 2018). "As CCR8 promotes T cell trafficking to the skin, it is intriguing that this chemokine receptor is abundant on CD26high T cells from melanoma patients." (PMID 29213079, 2017). "Another chemokine, CCL1, was shown to promote lymph node entry of melanoma cells expressing the receptor CCR8, whereas blocking of CCR8 function resulted in decreased lymph node metastasis." (PMID 28590032, 2017). "In a recent study it was reported that CCR8 is expressed in Tregs whereas another study using a melanoma model reported that CCR8 is expressed on tumor cells." (PMID 25853550, 2015). "CCL1 is produced by SCS LECs and mediated entry of CCR8+ melanoma cells into LNs." (PMID 29527513, 2018). "We next assessed CCR8 expression on tumor-infiltrating T cells from freshly resected human NSCLC and melanoma tumor samples." (PMID 33589525, 2021). "CCL1 and CCL22, the main ligands for CCR8 and CCR4, respectively, have been shown to be upregulated both at the gene and protein levels in the TME of melanoma, suggesting that melanoma cells are able to actively recruit T-regs." (PMID 34830780, 2021). "Similarly, protein expression of CCR8 in human NSCLC and melanoma tumors was restricted to the activated (OX-40+) CD3+CD4+CD127−CD25+ ti-Tregs." (PMID 33589525, 2021). "As mentioned, CCR8 is thought to be a more selective marker for tumour-infiltrating T-regs, but the blockade of CCR8 does not appear to impact the number of T-regs infiltrating melanoma." (PMID 34830780, 2021). "Importantly, we had similar observations using the syngeneic B16‐F10 melanoma tumour model, growth of which was highly sensitive to Treg cell depletion but not to germline ablation of Ccr8." (PMID 33838058, 2021). "In Braf/Pten melanoma-draining LNs, TSLP promoted not only GATA3+ Th2 cells, but also GATA3+ Tregs expressing a specific signature including ST2, CCR8, ICOS, PD-1, CTLA-4, OX40, and IL-10 — but not Th2 cytokines IL-4 and IL-13." (PMID 36107619, 2022). "Here, using Ccr8−/− mice, we show that CCR8 function is not required for Treg cell accumulation or immunosuppression in the context of syngeneic MC38 colorectal adenocarcinoma and B16 melanoma tumours." (PMID 33838058, 2021). "Interestingly, CCR8 appears to be expressed on T-regs after TCR-mediated activation, and yet, it does not appear to be required for recruitment into melanoma tissues." (PMID 34830780, 2021).
colorectal cancer (12 papers, 2019 to 2025). A primary or metastatic malignant neoplasm that affects the colon or rectum. "Lastly, in addition to the colorectal cancer, CCR8+ Tregs presence has been demonstrated in such major types of cancer as breast, hepatocellular carcinoma, non-small cell lung cancer and metastatic melanoma." (PMID 41035646, 2025). "The in vivo behavior of whole anti-CCR8 IgG and its fragments was compared in two diverse models of murine colorectal cancer—MC38 tumors in C57Bl6 mice and CT26 tumors in Balb/c mice." (PMID 41302499, 2025). "We then proceeded to radiolabeling the Fab fragments and whole anti-CCR8 IgG with an imaging radionuclide 111Indium (111In) for the subsequent in vivo imaging in colorectal cancer murine models." (PMID 41302499, 2025). "Recently, the transcriptome of ti-Tregs in several cancers including colorectal cancer has been reported, which demonstrated the consistent upregulation of the CCR8 gene." (PMID 41302499, 2025). "Here, we revealed that a high level of TNF-α in the colorectal cancer (CRC) microenvironment upregulated CCR8 expression in Tregs via the TNFR2/NF-κB signalling pathway and the FOXP3 transcription factor." (PMID 37935468, 2024). "Recent studies have shown that, compared with tissue-resident Tregs in normal tissues, CCR8 is particularly high in tumor-resident Tregs in breast cancer, colorectal cancer and lung cancer patients." (PMID 34884642, 2021). "The results showed that CCR8 has the potential to be a new target for colorectal cancer immunotherapy." (PMID 34884642, 2021). "It has been reported that CCR8 can be used as a specific marker which could be selectively upregulated on infiltrating Tregs in a variety of cancers, including lung, breast, colorectal cancer and so on." (PMID 37950246, 2023). "We have recently demonstrated that an anti-CCR8 antibody armed with alpha particles emitter 225Actinium (225Ac) was able to efficiently kill CCR8+ ti-Tregs in CT26 and MC38 murine models of colorectal cancer." (PMID 41302499, 2025). "We have recently demonstrated for the first time that an anti-CCR8 antibody armed with alpha particles emitter 225Ac was able to efficiently kill CCR8+ ti-Tregs in CT26 and MC38 murine models of colorectal cancer." (PMID 41302499, 2025). "CCR8 facilitates Treg migration to the TME, with high CCR8 expression on Tregs infiltrating solid tumors such as breast, lung, and colorectal cancers." (PMID 39000453, 2024).
asthma (11 papers, 2008 to 2026). "TL1A inhibition disrupts CCL8/C-C motif chemokine receptor 8 signaling and pathogenic T-cell responses, providing a precision medicine strategy for asthma." (PMID 41970030, 2026). "CCR8-deficient mice have a marked reduction of airway eosinophil infiltration and allergen-induced airway hyperresponsiveness, but the CCR8 is not essential for the development of airway inflammation in other animal models of asthma." (PMID 18315837, 2008). "It has been reported that CCR8 is predominantly expressed in T helper type 2 (Th2) cells and that CCL1/CCL8-CCR8 signaling is an important pathway in the pathogenesis of several type 2 related inflammatory diseases including asthma and atopic dermatitis." (PMID 33613532, 2020). "Our findings suggest that this may be due in part to alterations in CCR8 expression, which plays a key role in T cell homing to lung parenchyma and bronchial epithelium and has been implicated as an important factor in allergic inflammation and normal immune homeostasis in asthma." (PMID 23533402, 2013). "CCR8 is preferentially expressed on T-helper type 2 cells, and is thought to play a role in the pathogenesis of human asthma." (PMID 20455898, 2010). "Three reports have been published of CCR8 expression in the airways in asthma, all studying bronchial biopsies." (PMID 20455898, 2010). "In subjects with asthma, 29.8±3.5% and 36±3.5% of the IL-4+ and IL-13+ blood T cells expressed CCR8 while only 4.3±1.0% of IFN-γ+ cells expressed CCR8 (P<0.001)." (PMID 20455898, 2010). "In asthma, CCR8 was expressed by 30.3±3.0% and 28.9±7.8% of the IL-4+- and IL-13+-producing BAL CD3+ cells, respectively." (PMID 20455898, 2010). "We have used two reagents, a highly selective monoclonal antibody to CCR8 developed by ICOS Corporation and fluorescently labelled CCL1 (Millennium Pharmaceuticals), to study the involvement of CCL1 and its receptor CCR8 in asthma." (PMID 20455898, 2010). "This study therefore provides further evidence for a potential role for CCR8 in lung T cell recruitment in clinical asthma." (PMID 20455898, 2010). "Previous reports of CCR8 in human asthma had been difficult to interpret due to the poor specificity of the anti-CCR8 antibody used." (PMID 20455898, 2010). "CCR8 may represent a potential target for treatment of asthma and other allergic diseases and it was demonstrated that CCR8 served as a co-receptor for diverse T-cell tropic, dual-tropic, and macrophage-tropic HIV-1 strains." (PMID 32708796, 2020). "Also, chemokine receptors like CCR3, CCR4, and CCR8 have been found to be elevated in asthma patients and experimental murine models." (PMID 27795621, 2016). "Our study provides evidence that CCR8 may be involved in human asthma and may contribute to its pathogenesis in part through its role in trafficking TH2 cells to the lung." (PMID 20455898, 2010). "The CCR8 inhibitor (ML604086) developed by MedImmune (Gaithersburg, MD, USA) was previously developed with the aim to treat asthma marked by infiltration of a high number of eosinophils and Th2 cells responsible for the disease." (PMID 33924428, 2021). "Additionally, chemokine receptors such as C-C chemokine receptor 3 (CCR3), C-C chemokine receptor 4 (CCR4), C-C chemokine receptor 8 (CCR8) and C-X-C chemokine receptor 4 (CXCR4) are also key in Th2-driven asthma." (PMID 39664985, 2024). "Additionally, the regulation of the CCR8 GATA3 receptor facilitates the migration of Tregs to the inflammatory site, thereby promoting asthma control." (PMID 38666018, 2024). "CCR8 expression in blood and BAL from asthma and normal subjects was studied using flow cytometry." (PMID 20455898, 2010). "There have also been reports of CCL-17 (found at higher levels in asthma BAL compared with normal controls) being a ligand for CCR8, although this observation was not supported by another group." (PMID 20455898, 2010).
glioblastoma (11 papers, 2019 to 2025). The most malignant astrocytic tumor (WHO grade IV). "In glioblastoma, it was shown that the chemokine receptor CCR8 acts as a docking site for tumor-derived EVs." (PMID 39698539, 2024). "This study shows CCR8’s involvement in the EV-mediated transfer of chemoresistance-determining factors between glioblastoma cells." (PMID 39698539, 2024). "CCR8 acts as an EV receptor on glioblastoma cells and binds to CCL18, which acts as a bridging molecule." (PMID 30925930, 2019). "Furthermore, lactylation modification had been investigated in immunotherapy, for example, CCR8 lactylation can impair the effectiveness of CAR-T therapy against glioblastoma." (PMID 41035644, 2025). "In glioblastoma (GBM), tumor-derived lactate induces H3K18 lactylation, leading to increased expression of CD39, CD73, and CCR8." (PMID 39662177, 2024). "This phenomenon could be reversed by pharmacological inhibition of CCR8 with the small molecule R243, inhibiting EV uptake by GBM cells, resulting in sensitization of glioblastoma cells to TMZ." (PMID 30925930, 2019).